IL6 (interleukin 6)
Diseases named in the same sentence as IL6 in open-access papers (continued):
Sharing a sentence is not in itself a finding about the gene and the disease.
tumor (continued). "Sarcomas growing in Ptx3−/− host showed a much higher macrophage and neutrophil infiltrate, and higher levels of CCL2, CXCL2, TNFα, IL-6, IL-1β, and VEGF, suggesting an exacerbated tumor-associated inflammatory response." (PMID 26075183, 2015). "To determine the effects of IL-6 nAb on MCF10.DCIS structures, we examined the expression of a panel of candidate genes that have been associated with tumor growth and invasion." (PMID 26268945, 2015). "We showed that CAFs are an important IL-6 source and that anti-IL-6 receptor antibody suppressed angiogenesis and inhibited tumor-stroma interactions." (PMID 26690480, 2015). "A recent report indicated that dietary iron enhanced the colonic IL-6/IL-11-STAT3 signalling pathway and promoted inflammation and subsequent tumour development in a mouse model of inflammation-associated colorectal tumourigenesis using DSS38." (PMID 28781374, 2015). "EGFR signaling regulates the proliferation and tumorigenic ability of GSCs by inducing ID3 and ID3-regulated cytokines (GRO1, IL-6, and IL-8), which play a crucial role to make the tumor microenvironment suitable for GSC maintenance." (PMID 26437223, 2015). "In conclusion, we demonstrate that thermal ablation of normal organ parenchyma (such as is required in clinical practice) can result in Interleukin-6-mediated locoregional and systemic effects (including distant tumor growth)." (PMID 26154425, 2015). "Blocking IL-6 signalling with an anti-interleukin-6 receptor antibody or inhibiting IL-6 trans-signalling with TGF-β has also been shown to suppress tumour progression in colon cancer." (PMID 26446703, 2015). "All of these phenomena are related to the complex tumor microenvironment, as many of its components, such as IL-6, HIF-1α, and TGF-β, are concerned with induction and maintenance of CSCs." (PMID 26705466, 2015). "We found that STC1 was upregulated in the tumor tissues and its expression levels was positively correlated with the levels of interleukin (IL)-6 and IL-8." (PMID 26469082, 2015). "The IL-6 level significantly increased in tumor-bearing mice after chemotherapy, suggesting that both chemotherapeutic agent-induced IL-6 and myostatin promote muscle atrophy." (PMID 25797259, 2015). "Tumor cells also express EBV-encoded LMP1, which was demonstrated to regulate the production of IL-6 in epithelial cells, and IL-6 is able to promote NPC progression and increase hs-CRP levels." (PMID 25874450, 2015). "Together with CCL2 chemokine, IL-6 is the pro-inflammatory and tumor-promoting cytokine that we have seen consistently upregulated in our tumor model by the different cell types examined or their crosstalk." (PMID 25599228, 2015). "Co-deletion of IL-6 and Pten triggered early lethality, progressive high-grade adenocarcinoma formation with increased tumour growth and weight, resulting in disseminated metastases, for example, in the liver." (PMID 26198641, 2015). "There are many cytokines secreted by aHSCs that are associated with tumor invasion and metastasis, including HGF, EGF, IL-1, IL-2, IL-6, MMP-2, MMP-9, TGF-β, TNF-α, VEGF and members of the Wnt signaling family." (PMID 26517671, 2015). "On the one hand, IL-6 stimulated tumor cell survival and negatively regulated the antitumor immune response in mice bearing Colo26 xenografts." (PMID 26516076, 2015). "Evidence of IL6 expression in the tumor stroma of primary ES and dismal prognosis of patients presenting with higher IL6 levels at diagnosis further suggest a biological relevance of this cytokine in ES pathogenesis." (PMID 26215971, 2015). "Since these cells secrete IL-6, which is a major player in breast carcinogenesis, especially the carcinoma-stroma reciprocal interplay, we sought to investigate the possible role of p16 in repressing the expression of IL-6." (PMID 26338965, 2015).
tumor (continued). "Adjuvant MNP anti-IL6 siRNA post-ablation reduced the tumor growth rate such that endpoint diameter was significantly smaller than hepatic ablation alone, and equal to the sham arm (vs. RFA alone p = 0.009, vs. sham p = 0.94)." (PMID 26154425, 2015). "EAT growth stimulated release of IL-6 in the 13th day of tumor growth, whereas treatment with indomethacin of tumor-bearing animals inhibited the release of this cytokine at the same time of tumor growth." (PMID 26347589, 2015). "Blocking of the STAT3 signaling abrogated IL-6-induced Jagged-1 expression, effectively inhibited the growth of the trastuzumab resistant cells, and enhanced the anti-tumor activities of trastuzumab in the resistant cells." (PMID 25669984, 2015). "Several cytokines such as macrophage migratory inhibitory factor (MIF), TNF-α, IL-6, IL-17, IL-12, IL-23, IL-10, and TGF-β have been associated with both experimental and human cancers and can either promote or inhibit tumor development." (PMID 26511466, 2015). "We found IL-6 instead of VEGF expressed obvious correlation not only with tumor severity but also with deteriorating liver preservation." (PMID 25908103, 2015). "We have recently demonstrated that endothelial cell-secreted IL-6 regulates the rate of tumor growth via STAT3 signaling." (PMID 26287605, 2015). "Expression profiling of different cellular constituents of tumors indicated that HGF mRNA was predominantly expressed by CAFs and ECs while IL-6 mRNA was mainly expressed by tumor cells and by CAFs." (PMID 25849942, 2015). "The amounts IL-6 gene expression in tumor tissues of tumor-bearing mice are statistically significantly lower in groups TM, TB, and TX when compared to group TC (P < 0.05)." (PMID 26167490, 2015). "One of the most critical tumor-promoting cytokines in non-small cell lung cancer (NSCLC) is interleukin-6 (IL-6)." (PMID 25504436, 2015). "In the current study, we show that IL-6 expression can be found in both the tumor and stromal compartments." (PMID 26268945, 2015). "IL-6 is a pleiotropic cytokine that is involved in several stages of tumor development and can mediate epithelial-stromal interactions." (PMID 26010154, 2015). "This has been proposed to contribute to bone turnover as a result of CXCR4-mediated upregulation of IL-6, which is then secreted by the tumor cells to stimulate osteoclastogenesis, thereby enhancing tumor invasion." (PMID 25999952, 2015). "In mouse-xenografted experiments using cancer cells and CAF (Fig7A–B), or patient-derived tumours (Fig7B), IL-6 was co-expressed in α-SMA-positive cells." (PMID 25834145, 2015). "Similar to ES cell lines, of which 4 out of 9 expressed mRNA for IL6, only three of seven tumor biopsies expressed mRNA for IL6." (PMID 26215971, 2015). "The finding that TNF-α can stimulate ANXA2-dependent secretion of IL-6 in tumor cells suggests that ANXA2 can also modulate the tumor microenvironment." (PMID 25611381, 2015). "In the case of RMA tumour in aged mice, IFN-γ response of tumour (MuLV EnvH13.3)-specific CD4+ T cells was restored by IL-6 blockade." (PMID 25850032, 2015). "Subsequently, all the factors were down-regulated, and RT-PCR indicated that the expression ratios of seven weeks/five weeks of IL-6, IL-6R, and gp130 in tumor growth decreased by 0.43-fold, 0.47-fold, and 0.33-fold, respectively." (PMID 26525581, 2015). "Tumor-promoting cytokines released by immune/inflammatory cells, including IL-6, act in a paracrine manner to activate transcription factors, such as NF-κB, STAT3 and AP-1, to achieve their effects in many types of cancer cells." (PMID 25504436, 2015). "IL-6 expression was almost undetectable in tumours obtained from mice treated with gemcitabine + SOM230 bi-therapy, in correlation with the reduction in the α-SMA staining (Fig7A–B, Supplementary S12C–G)." (PMID 25834145, 2015).
tumor (continued). "Immunohistochemical analyses of serial tumour sections revealed that, whereas IL6-expressing regions largely overlapped with those for cytokeratin 6, a 4T1 cancer cell marker, they did not significantly overlap with those for CD45, an immune cell marker." (PMID 26671411, 2015). "Age, FIGO stage, histological type, residual tumor at the time of surgery, “high” IL-6 expression and “high” IL-6R expression were entered in this model." (PMID 25658637, 2015). "We used EMSA to detect constitutive NF-κB/STAT3 activity in BL- and MM-like neoplasms that spontaneously developed in single-transgenic IL6 (interleukin-6) or MYC (c-Myc) mice, or in double-transgenic IL6MYC mice." (PMID 25838973, 2015). "Even in aged mice tumour outgrowth was substantially diminished by donor OT-II cells primed concomitantly with IL-6 blockade when endogenous CD8+ T cells were retained." (PMID 25850032, 2015). "ELISA analysis revealed increased expression of STAT3-activating cytokines such as EGF, OSM and IL-6 in lungs harbouring KrasG12D-driven tumours compared with healthy control lungs." (PMID 25734337, 2015). "The purpose of this study was to investigate the relationship between serum levels of IL-6 and the severity and extent of the disease based on tumor stage and histological grade in order to explore use of this biomarker as a prognostic factor and tumor marker." (PMID 26082901, 2015). "Tumor necrosis factor TNF-α not only has a cytotoxicity and the growth inhibition on tumor cells, but also can mediate the production of IL-1, IL-6, and other inflammatory mediators to participate in the collective physiopathologic process." (PMID 26609318, 2015). "These pathways converge in autocrine or paracrine phosphorylation of STAT3, making IL-6 a key contributor to tumor growth, drug resistance, induction of cancer stem cells, and metastasis." (PMID 26512918, 2015). "Tumor growth is suppressed in IL-17 knockout mice and IL-17/IFN-γ double-knockout mice, and a mechanism for this knockout is that IL-17 induces the production of IL-6 by tumor cells, which in turn promotes tumor growth through a STAT3–dependent pathway." (PMID 25992978, 2015). "Third, VEGF works in concert with numerous signaling molecules such as angiopoietins, ephrins, hepatocyte growth factor, hypoxia-inducible factor, IL-6, and endostatin to promote tumor cell survival." (PMID 25810565, 2015). "The IL-6-IL6R and IL-6/sIL-6R complexes can heterodimerize with glycoprotein 130 (gp130) that is ubiquitously expressed by most cell types, including tumor cells." (PMID 26516076, 2015). "S100A9-mediated release of IL-6 requires the crosstalk of tumor cells with monocytes through the activation of NF-κB and STAT-3." (PMID 26315114, 2015). "The Western blot analysis also revealed the similar trend of IL-6, IL-6R and gp130 during tumor growth." (PMID 26525581, 2015). "Together, S100A9 promoted TW-2.6 tumor formation as well as dominant increase of myeloid cell marker and IL-6 expression in vivo." (PMID 26315114, 2015). "To further examine possible sources of IL6 in ES we used an αIL6 antibody to stain tumor specimens from 4 ES patients." (PMID 26215971, 2015). "Secretion of the chemokine MCP-1 generally attracts monocytes or macrophages (cell-mediated immunity), while the proinflammatory cytokine IL-6 activates B cells to produce tumor-specific antibodies (humoral immunity)." (PMID 26006716, 2015). "IL-6 also helps in binding CRP to phospholipids on tumor cells that results in activation of classic C1q complement pathway." (PMID 26693355, 2015). "The tumor cell survival is dependent of growth factors, like TNFα, IL1β, IL6 and VEGFα secreted by mast cells, macrophages and MDSCs." (PMID 25747113, 2015). "Since cytokines play a key role in controlling immune responses and inflammatory reactions, we employed the ELISA assay to investigate the effects of SCL on the production of serum cytokines, including TNF-α, IFN-γ, IL-2 and IL-6, in H22 tumor-bearing mice." (PMID 26426041, 2015).
tumor (continued). "IL-6 also stimulated recruitment of myeloid-derived suppressor cells, and induced invasive tumor in ESCC." (PMID 25934640, 2015). "Some cancer patients present high serum levels of TNF-a, IL-6, and IL-1 which correlate positively with the progression of some tumours." (PMID 26508818, 2015). "The results obtained in the measurement of cytokines showed that the EAT promoted release of IL-2 and IL-6 in the 13th day of tumor development." (PMID 26347589, 2015). "It proves the rationality of our results demonstrating the higher tumor clearance efficiency of miR-22 inhibited DCs with up-regulated IL-6 and Th17." (PMID 25826372, 2015). "They found the increased levels of IL-6 at the tumor leading edge and positively correlated with advanced stage, suggesting a mechanistic link between tumor cell production of IL-6 and invasion." (PMID 26258407, 2015). "Further studies evaluating the role of PCT and IL-6 at baseline in cancer patients, and correlation of serum biomarkers levels with progression and regression of the tumor as well as response to chemotherapy are warranted." (PMID 26148092, 2015). "On the other hand, the mRNA levels of IL-6 in tumor and adjacent non-tumor tissues were both significantly higher than normal controls (P = 0.0003 and P = 0.0002, respectively)." (PMID 26547929, 2015). "Cytokine IL-6 production of the monocytes was significantly higher in case of direct cell-cell (i.e., tumor-monocyte) contact compared to co-cultures where tumor cells and monocytes were separated by a semi-permeable membrane." (PMID 26343729, 2015). "The detection of IL-6 increase in vivo but not in vitro suggests a requirement of the crosstalk between tumor and stroma cells for the induced IL-6 expression in tumors." (PMID 26315114, 2015). "TNF-α, IL-1β and IL-6 play important roles in the tumor microenvironment and contribute to the promotion of inflammation associated carcinogenesis." (PMID 25763529, 2015). "Based on the function of IL-6 in inflammation-related carcinogenesis, we focused on the role of IL-6 in the conversion of hUC-MSCs into tumor-supporting cells." (PMID 25483835, 2015). "On the other hand, CRP is also upregulated by cytokines such as IL-6 and tumor necrosis factor, and this upregulation is considered to be a systemic reaction to tumor progression." (PMID 25602444, 2015). "In conclusion, we found that the three aliquots of the C26 tumor cell line maintained in our laboratory varied in expression of IL-6 mRNA and protein, and in development of cancer cachexia and fatigue-like behaviors in the tumor bearing mice." (PMID 25709898, 2015). "In patients with gastrointestinal cancer, plasma IL-6 levels significantly correlated with the presence of tumour and increased with each progressive stage of cancer." (PMID 26508820, 2015). "Since IL6 promotes cell dissemination in a great variety of tumors we thus analyzed migration of A4573/GFP ES tumor cells in CAM assays." (PMID 26215971, 2015). "A previous study also demonstrated that IL-6 is a key cytokine that induces MDSCs under tumour-bearing conditions." (PMID 28781374, 2015). "We generated MDSCs in vitro following a well-established protocol using IL-6 and GM-CSF, two factors secreted by tumors that recruit MDSCs from the BM to the circulation in tumor-bearing mice." (PMID 25982370, 2015). "The pleiotropic cytokine IL-6 is known to play central roles in various types of cancers as a tumor growth factor, and is one of the main factors also responsible for cancer-induced cachexia." (PMID 25599228, 2015). "IHC analysis of the harvested tumours indicated the corresponding changes of IRAK1 and IL-6 expressions in IRAK1-depleted tumours and in ectopic IRAK1-rescued tumours compared with control tumours, although cell proliferation marker Ki67 remained unchanged." (PMID 26503059, 2015).
tumor (continued). "Our in vivo system showed a significant positive correlation between tumor size and IL-6 secretion, supporting previous reports regarding the positive role of IL-6 in tumorigenesis." (PMID 25645622, 2015). "We utilized a 3D MAME culture model, to study the role of IL-6 signaling between human breast DCIS cells and human breast CAFs." (PMID 26268945, 2015). "In contrast to the expression of the IL6 receptor components in almost all ES cell lines and tumor samples, IL6 was found to be expressed in less than half of tumors applying RT-PCR." (PMID 26215971, 2015). "Composite results show that daily oral intake of celecoxib in tumor-bearing mice can lower the amounts of M-CSF, IL-6, IL-10, COX-2, and TGF-β gene expression in tumors of tumor-bearing mice." (PMID 26167490, 2015). "As a chemotactic factor, SDF-1α has been reported to stimulate endothelial cells, fibroblasts and tumor cells to secrete a variety of factors, such as IL-6, IL-8, and matrix metalloproteinases (MMP)." (PMID 25609203, 2015). "Inflammatory responses depend on both hematopoietic cells and the capacity of tumor cells to secrete IL-6 in an autocrine and paracrine manner." (PMID 25897427, 2015). "IL-6 has been reported to be increased in a variety of tumours, contributing to aggressive tumour growth and resistance to treatment." (PMID 25705130, 2015). "IL-6 promotes angiogenesis and the expression of VEGF through JAK2/STAT3 signaling and the tumor promoting effects of IL-17 are in part mediated through upregulation of IL-6." (PMID 26648665, 2015). "The three aliquots of the C26 tumor line showed differences in IL-6 mRNA and protein secretion in vitro, with aliquot β showing the greatest IL-6 secretion." (PMID 25709898, 2015). "In fact, IL-6 enhanced tumor survival post-PDT by negatively regulating anti-tumor immune memory and eliciting anti-apoptotic effects." (PMID 26307977, 2015). "Tumor-derived factors like IL10, IL6, CSF1, and VEGF interfere with DC maturation, causing failure to migrate to the tumor-draining lymphoid organs, and to provide the appropriate co-stimulatory signals required to stimulate T cells." (PMID 26500653, 2015). "An underlying mechanism for DCIS:CAF interaction, enhanced tumor cell proliferation, and migration was IL-6 signaling in the tumor microenvironment." (PMID 26268945, 2015). "Interleukin 6 (IL-6) is a major activator of the Stat3 signaling pathway, which is involved in tumor growth and aggressiveness in various cancers, including BC." (PMID 26729098, 2015). "More to the point, Bcl-2, when co-cultured with head and neck tumor cells (CAL27), significantly enhanced EMT-related changes in tumor cells, predominantly through secretion of IL-6." (PMID 25590298, 2015). "We further analyzed the expression of several molecules in tumor tissues to determine the relationship between IL-6 and cisplatin sensitivity." (PMID 26313152, 2015). "Cytokine profiles were entirely different when NSG animals were implanted with tumor alone (PC3-bearing NSG), where only tumor-derived IL-6 and IL-8 were detected in the serum." (PMID 25901284, 2015). "Lentiviral-based STC1 overexpression in Hep3B and MHCC-97L cells however showed inhibitory action on the pro-migratory effects of IL-6 and IL-8 and reduced size of tumor spheroids." (PMID 26469082, 2015). "Many tumor-produced factors, such as IL-10, IL-6 and VEGF, activate STAT3 by efficient feed-forward mechanisms." (PMID 26512963, 2015). "Comparing the expression status of IL-6 in EOC tissues with that in normal samples, we found significantly higher levels of the IL-6 expression in tumor tissues (p < 0.0001)." (PMID 26282935, 2015). "The levels of serum IL-6 and IL-1β in tumor bearing mice slightly increased after the docetaxel treatment, suggesting that docetaxel exacerbates these side effects." (PMID 25797259, 2015). "We specifically inhibited autocrine and paracrine IL-6 signaling to determine its contribution to early stage tumor progression." (PMID 26268945, 2015).